CEBPD (CCAAT enhancer binding protein delta)
Diseases named in the same sentence as CEBPD in open-access papers (continued):
Sharing a sentence is not in itself a finding about the gene and the disease.
tumor (continued). "Under the suppression of CEBPδ expression, both Vtn and ZC3H12D expression were increased in B220+CD11c+NK1.1+ NK cells derived from tumor-bearing mice livers 48 h after the siRNAs were administered." (PMID 36890150, 2023). "We began this study after observing that the transcription factor C/EBPδ (CEBPD) was highly expressed in IBC cell lines and in parenchymal tumor cell emboli of patient tissues." (PMID 36757813, 2023). "Following CEBPδ-siRNA treatment, fluorescently labeled liver CD45+ cells from tumor-free and tumor-bearing mice were injected into the tail veins of individual mice, and CD45+ cell accumulation in the liver and lungs was quantified." (PMID 36890150, 2023). "The transcription factor CCAAT/enhancer binding protein delta (CEBPD) activates the PTX3 gene in stromal cells, contributing to cancer and chemoresistant tumour progression." (PMID 35090088, 2022). "Examples of genes with more expression per cell in the erlotinib-treated group are PLAAT3, LCN2, CEBPD, and SAA1; conversely, LDHB is shown as an example for transcripts more abundant in control tumor cells." (PMID 36482068, 2022). "To corroborate the in vitro data, we used the tumor xenografts from HFD-fed mice to clarify the expression of pSTAT3, CEBPD, and MCL1." (PMID 34156978, 2021). "The knockdown of CEBPD in U373MG and T98G cells significantly reduced the area and number of tumor spheroids after IL-1β treatment." (PMID 31300060, 2019). "In an attempt to examine the interaction of MK2 with RBPs, we determined expression of MK2-regulated RBPs (CEBPδ, AUF1, HuR, CUGBP1, and TTP) using IHC and found their elevated expression and activation in tumor samples." (PMID 31023373, 2019). "Among these CEBPD-responsive genes, PDGFA (platelet-derived growth factor subunit A), downregulated in CEBPD-knockdown U373MG cells, was of great interest in our study because of its critical role in tumor progression." (PMID 31300060, 2019). "Hypoxia levels were reduced in tumor cells, resulting in decreased levels of metastasis-promoting genes (MMPs, VEGFs, FGF2, and CEBPD) thus impairing metastasis." (PMID 26010068, 2015). "In addition, our co-regulated subnetwork for MES tumors confirmed the established role of the hypoxic tumor microenvironment, as suggested by the inclusion of EPAS1 and CEBPD, both master TFs for hypoxia-regulated genes in GBM46,47." (PMID 40234567, 2025). "Precancerous clusters showed enrichment in tumor progression-related regulons, including transcription factors (TFs) linked to tumor proliferation and cell cycle progression (STAT1, BCL6, ETV5) and potential tumor suppressors (ELF5, LTF, RXRG, CEBPD), as well as EMT-related regulons." (PMID 39872221, 2025). "This context-specific axis offers targeted opportunities, like TNFRSF1A or CEBPD inhibition, to block mesenchymal invasion without impacting core tumor pathways." (PMID 41235227, 2025). "Additionally, the CEBPD/ VAMP3 axis increases extracellular PD-L1 levels via the paracrine EVs, consequently dampening the anti-tumor immune response." (PMID 38627816, 2024). "Because NK cells are very sensitive to environmental factors and these factors differ during the primary tumor progression, it is not surprising that gene expressions controlled by the CEBPδ-Hnf1α axis changed in a primary tumor size-dependent manner." (PMID 36890150, 2023). "Aside from the importance of CEBPD expression in cancer cells to tumor progression, the impact of non-cancer cells with CEBPD on the regulation of malignant aggressiveness has been paid close attention to recently." (PMID 36776299, 2023). "Additionally, our previous studies have also indicated that PTX3 is a downstream target of CEBPD and that the CEBPD/PTX3 axis is involved in some inflammation-related diseases and even in the tumor progression." (PMID 36530573, 2022).
tumor (continued). "Furthermore, to investigate the relationship among BMI and leptin levels and OBR, pSTAT3, CEBPD, and MCL1 expression, patient serum and tumor specimens were evaluated by ELISA and IHC, respectively." (PMID 34156978, 2021). "In BFTC909‐xenografted SCID/beige mice without induced DM, the tumour size of the CEBPD‐overexpressing group was larger than that of the mock group." (PMID 34954904, 2021). "Although of obvious interest, whole tumor biopsy CEBPD expression levels do not necessarily correspond to C/EBPδ activity in tumor cells." (PMID 32906832, 2020). "Moreover, comparing with their individual controls (compare lane 1 with lane 2 and lane 3 with lane 4), loss of CEBPD significantly enhanced the growth of xenografted Huh7 tumor in NOD-SCID mice, suggesting that CEBPD indeed plays an antitumor role." (PMID 28099155, 2017). "Real-time RT-PCR revealed that expression levels of CEBPD (P<0.001) were most significantly upregulated in tumor samples featuring gains on 8q11.21 followed by KIAA0146 (P=0.023) (Figure-1D), thereby reinforcing the role of CEBPD as an amplification-driven gene in UBUC." (PMID 26307680, 2015). "Particularly, the mRNA level of CEBPD showed a stepwise escalation from non‐tumour urothelium, non‐muscle invasive bladder cancer (NMIBC), to muscle invasive bladder cancer (MIBC) (NMIBC vs. Normal, p < .001; MIBC vs. Normal, p = .048; MIBC vs. NMIBC, p = .006)." (PMID 34954904, 2021). "CEBPD mRNA expression was observed in both tumor and non-tumor tissue in both datasets analyzed." (PMID 32906832, 2020). "Thus, although CEBPδ is expressed with low tissue specificity, not an NK cell-specific transcription factor, it is highly like those signaling pathways where the CEBPδ-Hnf1α axis is involved are unique to the anti-tumor NK cells." (PMID 36890150, 2023). "Furthermore, the clinical correlations showed that the higher level of VEGFA or MVD has a positive correlation with the expression of CEBPD and a negative relation to hsa-miR-429 and leads to tumor aggressiveness with worse disease-specific, metastasis-free survival in UBUC and UTUC cohorts." (PMID 35203290, 2022). "In addition to confounding expression of CEBPD in stromal cells, expression levels in whole tumor biopsies may also not fully represent nuclear C/EBPδ activity." (PMID 32906832, 2020).
cancer (80 papers, 2010 to 2026). A tumor composed of atypical neoplastic, often pleomorphic cells that invade other tissues. "Radiotherapy is part of the standard of care for GBM and other cancers and significantly, ATF5, CEBPB and CEBPD have been associated with cancer cell radiation resistance." (PMID 36831248, 2023). "We found that the activation of CEBPD in M2-like macrophages and CAFs contributed to stemness and the migration and invasion of cancer cells that were both susceptible and resistant to drugs." (PMID 26124179, 2015). "Moreover, in various cells, including cancer‐associated stromal cells, the transcription factor CEBPD is responsive to external stimuli, such as inflammatory factors, stressors and chemotherapeutic drugs." (PMID 35090088, 2022). "CEBPD plays a pivotal role in controlling cellular anti-apoptotic processes, migration, reactive oxygen species generation, and cancer development, modulating these activities based on cell type and environmental conditions." (PMID 40452847, 2025). "CEBPD inhibits the proliferation, migration, and invasion of cancer cells while promoting apoptosis (Chan, Shiue & Li, 2023)." (PMID 40895068, 2025). "It provides a fresh outlook on targeting EPCs for BC treatment and supports CEBPD as a potential cancer therapeutic target." (PMID 40114930, 2025). "Our findings show that pre-treatment with Dpep, a cell-penetrating peptide designed to target the transcription factors ATF5, CEBPB, and CEBPD, sensitizes a variety of cultured cancer cells to the cytotoxic activity of NK-92MI cells." (PMID 40358191, 2025). "The CEBPD transcription factor enhances cancer resistance through VAMP3-mediated autophagy activation, increasing PD-L1 levels and suppressing CD8+ T-cell-mediated immune response." (PMID 39409003, 2024). "Previous studies reported that CEBPD negatively regulated FBXW7 gene expression in cancer cells and was essential for the acquisition of cancer stemness properties." (PMID 38892210, 2024). "Several studies indicate that CEBPB and CEBPD promote metabolic reprogramming and affect glycolysis in various cancer cell types." (PMID 38920655, 2024). "In prostate cancer, CEBPD is involved in cancer stemness, metastasis, and resistance to anti-cancer drugs." (PMID 38892210, 2024). "CEBPD, an acronym denoting the CCAAT/enhancer-binding protein delta, emerges as a pivotal transcription factor with significant implications in cancer initiation and advancement." (PMID 38926832, 2024). "As will be discussed here, the leucine zippers of ATF5, CEBPB and CEBPD are key features in the design of cell-penetrating decoy peptides to target them for brain and other cancers." (PMID 36831248, 2023). "CEBPD is a leucine zipper transcription factor that can promote malignant biological behavior in various cancer types." (PMID 37017469, 2023). "In consonance with past reports cited above in which interference with ATF5, CEBPB or CEBPD expression suppressed migration of cancer cells." (PMID 36831248, 2023). "In this review, we relate how ATF5 and then CEBPB and CEBPD were identified as targets for treatment of brain and other cancers." (PMID 36831248, 2023). "The involvement of TGF‐β1 and CEBPD in metastasis, promoting stemness and chemoresistance in cancer cells, has been previously suggested." (PMID 35090088, 2022). "CCAAT/enhancer-binding protein delta (CEBPD) is a transcription factor that plays important roles in inflammatory disease and cancer development." (PMID 36035213, 2022). "We also assessed the relationship of TGF‐β1‐induced CEBPD activation in BCAFs and its contribution to cancer stemness." (PMID 35090088, 2022). "We further assessed the in vivo effects of stromal CEBPD activation in cancer cells in response to CDDP treatment." (PMID 33953165, 2021). "CCAAT/enhancer-binding protein delta (CEBPD), an inflammation-responsive transcription factor, has been recognized as an essential player in inflammatory disease and cancer progression." (PMID 33436575, 2021).
cancer (continued). "The inactivation of CEBPD has been observed in several types of cancers, including cervical cancer, hepatocellular carcinoma, breast cancer, prostate cancer, and leukemia." (PMID 34156978, 2021). "HPV+ SiHa cancer cells expressed high levels of CEBPD, SLPI, and PPL mRNA relative to HFKs and HPV-C33A cancer cells." (PMID 34944802, 2021). "Together, these findings indicate that Bpep/Dpep reduce expression of well-defined ATF5, CEBPB and CEBPD targets with cancer relevance." (PMID 34065488, 2021). "The gene-regulatory factors ATF5, CEBPB and CEBPD promote survival, growth, metastasis and treatment resistance of a range of cancer cell types." (PMID 34065488, 2021). "PTX3 is involved in CEBPD-induced acquired chemoresistance, stemness, and metastasis/invasion of cancer cells." (PMID 30740360, 2019). "In this review, we highlighted the role of CEBPD during inflammation and inflammation-related diseases, including cancers." (PMID 25591788, 2015). "To illuminate potential cellular pathway mediators for cancer invasiveness regulated by CEBPD, we used RT2 ProfilerTM PCR arrays to examine the differences in transcript levels of selected signaling molecules involved in metastasis." (PMID 26307680, 2015). "We further assessed the in vivo effects of activated CEBPD in stroma on the CDDP treatment of CDDP-resistant cancer cells." (PMID 26124179, 2015). "We further developed a PTX3 inhibitor RI37 peptide to prevent CEBPD/PTX3 axis-induced cancer malignancies and reduce the metastasis and invasion of drug-resistant cancers." (PMID 26124179, 2015). "We showed that the activation of CEBPD in M2 macrophages and myofibroblasts/CAFs promoted sphere-forming ability and the metastasis and invasion of both responsive and drug-resistant cancers." (PMID 26124179, 2015). "Our data suggest that CEBPD plays an important role in microenvironment-mediated cancer progression." (PMID 26124179, 2015). "RT-PCR results showed that the expression levels of CCL19, CD24, and ZIC2 were significantly higher in the MCF-7, ZR-75-1, and SK-BR-3 cell lines compared to the reference MCF-10A group, whereas the transcription level of CEBPD was significantly lower in the cancer cell lines (p < 0.05)." (PMID 40895068, 2025). "It is anticipated that a better understanding of the proximal transcriptional events triggered by cell-penetrating peptides that target ATF5, CEBPB and CEBPD will better define their mechanisms of action, which in turn will inform their best use in therapies for treatment of brain and other cancers." (PMID 36831248, 2023). "ATF5, CEBPB and CEBPD have been reported to contribute to cancer cell radiation resistance." (PMID 34065488, 2021). "HCV-induced CEBPD expression confers a survival advantage to cancer cells encountering ER stress." (PMID 34680563, 2021). "In these cancer cells, CEBPD can promote drug resistance, invasion, and lymphangiogenesis." (PMID 31300060, 2019). "Moreover, a cancer cell allograft mouse model provided evidence to support the idea that CEBPD plays a role in cancer growth in the protumor microenvironment." (PMID 25591788, 2015). "CCAAT/enhancer binding protein delta (CEBPD) is a transcription factor implicated in physiological processes such as cell differentiation, metabolism, inflammation, growth arrest and cell death, yet its role in cancer remains much debated." (PMID 26307680, 2015). "In addition, the hypoxia environment in cancer can induce CEBPD expression and contributes to the metastasis and invasion of cancer cells." (PMID 25591788, 2015). "Insufficient activation of CEBPD in cancer cells has been suggested to induce genomic instability." (PMID 26124179, 2015).
cancer (continued). "Therefore, K+ channel inhibitors may be useful as novel agents that suppress the CEBPD pathway and may reverse c-Myc-mediated cancer stemness by up-regulating FBXW7." (PMID 38892210, 2024). "While this review focuses on ATF5, CEBPB and CEBPD in the context of brain cancers, it is important to consider, as we briefly do here, the roles of these transcription factors in other types of cancers and how the targeted peptide drugs discussed here may be used to treat these as well." (PMID 36831248, 2023). "miR-324-5p via PTPRD/CEBPD axis could participate in the progression of cancer via VEGF." (PMID 36035118, 2022). "Recently, our previous studies have demonstrated that PTX3 is a downstream target of CEBPD and contributes to inflammation-related disorders, such as atherosclerosis, Alzheimer's disease, rheumatoid arthritis, invasion and metastasis of cancer, and drug-resistant cancers." (PMID 36530573, 2022). "Here, we characterized the in vitro and in vivo anti-cancer efficacy of novel synthetic cell-penetrating peptides (Bpep and Dpep) designed to interfere with the formation of active leucine-zipper-based dimers by CEBPB and CEBPD, transcription factors implicated in multiple malignancies." (PMID 34065488, 2021). "We determined that activation of the CCAAT/enhancer binding protein delta (CEBPD) response to Cisplatin and 5-Fluorouracil in cancer-associated macrophages and fibroblasts contributed to the metastasis, invasion, acquired chemoresistance and stemness of cancer cells by in vitro and in vivo assays." (PMID 26124179, 2015). "The cell-penetrating ATF5/CEBPB/CEBPD inhibitor peptide Dpep upregulates TXNIP mRNA and protein in the majority of cancer cell lines surveyed." (PMID 38920655, 2024). "CEBPD has been identified as a regulator of MMP1, MMP3, and MMP9 in the gene profiles of cancer cells." (PMID 38419037, 2024). "These gene sets contain several genes that have been widely studied in the context of cancer, including WNT16, CEBPD and EGFR." (PMID 37381036, 2023). "EDN1, CEBPD, and CTNNB1 are key players in triggering cancer-promoting pathways, including EMT and Wnt/β-catenin signaling pathways." (PMID 34680563, 2021). "Our results show that CEBPD can directly bind to the SOX2, OCT4, NANOG, and ABCA1 promoter regions to promote the properties of cancer stemness and drug resistance." (PMID 33436575, 2021). "CCAAT enhancer binding proteins (CEBPs) including CEBPA, CEBPB, CEBPD, CEBPE, CEBPG and CEBPZ, are suggested as potential biomarkers for cancer prognosis." (PMID 34743716, 2021). "Thus, activating CEBPD expression in cancer cells could be a strategy for cancer therapy." (PMID 28099155, 2017). "We have developed cell-penetrating peptides that target the transcription factors ATF5, CEBPB, and CEBPD and that promote apoptotic cancer cell death both in vitro and in vivo without apparent toxicity to non-transformed cells." (PMID 40358191, 2025). "We have designed cell-penetrating peptides that target the leucine zipper transcription factors ATF5, CEBPB and CEBPD and that promote apoptotic death of a wide range of cancer cell types, but not normal cells, in vitro and in vivo." (PMID 38920655, 2024). "CEBPD upregulation via the p38/CREB pathway with HMDB as an activator was shown to activate PPPARG2 and chop GADD153 while attenuating E2F1, leading to the death of cancer cells." (PMID 37047552, 2023). "This CEBPD and MYC‐centric multilayered positive feedback loop enhances oncogenic glycolysis, which ensures cancer growth, especially during glucose metabolism dysregulation, indicating that it could be a target for combined treatment strategies." (PMID 34954904, 2021). "These novel CEBPD‐ and MYC‐centric multilayered positive feedback loops enhance cancer growth that could complement theranostic approaches." (PMID 34954904, 2021).
cancer (continued). "In the current study, we demonstrated a novel function of CEBPD: the molecule plays a protumor role in noncancerous cell types, such as fibroblasts and macrophages, in the context of the cancer microenvironment." (PMID 26124179, 2015). "Interestingly, in contrast to reports on other cancer types, CEBPD promoter methylation was seldom identified in cancer tissue (10%) and not identified in UBUC cell lines (Figure-2J-2L, Figure-S2, and Table-S5)." (PMID 26307680, 2015). "There are many potential advantages of using combination treatments rather than monotherapies for cancer treatment, and findings thus far indicate that this is so for cell-penetrating ATF5, CEBPB and CEBPD decoy peptides." (PMID 36831248, 2023).
infection (9 papers, 2015 to 2023). The state of being infected such as from the introduction of a foreign agent such as serum, vaccine, antigenic substance or organism. "This analysis identified a signature for 4 genes, CEBPD (0.93 log2FC), MAFB (0.83 log2FC), IFITM3 (0.55 log2FC), and LGALS1 (−0.53 log2FC), that was markedly enriched in CD14 monocytes in patients who ultimately survived infection." (PMID 35169146, 2022).
neurological disease (4 papers, 2013 to 2024). "CEBPD is an inflammatory transcription factor that contributes to the progression of neurological diseases." (PMID 38419037, 2024). "CCAAT/Enhancer-Binding Protein Delta (CEBPD) is an inflammatory transcription factor that contributes to neurological disease progression." (PMID 38419037, 2024).
inflammation (2 papers, 2016 to 2022). Aberrant reaction of the microcirculation characterized by movement of fluid and leukocytes from the blood into extravascular tissues. "CCAAT/enhancer binding protein delta (CEBPD) is a pivotal transcription factor in brain inflammation and is a member of CCAAT/enhancer binding protein (C/EBP) family." (PMID 26208701, 2016).